PAK4 (p21 (RAC1) activated kinase 4)
Diseases named in the same sentence as PAK4 in open-access papers (continued):
Sharing a sentence is not in itself a finding about the gene and the disease.
ovarian cancer (continued). "Earlier studies including ours have found higher Pak4 expression contributing to poor prognosis in patients of ovarian cancer and oral squamous-cell carcinoma." (PMID 26218748, 2015). "In our previous study, besides cell migration executed in the cytoplasm, we have revealed regulation of gene transcription by nuclear Pak4 in ovarian cancer." (PMID 26218748, 2015). "Pak4 also induce ovarian cancer cell proliferation through the Pak4/c-Src/EGFR/cyclin D1/CDC25A pathway." (PMID 26218748, 2015). "CDK5 kinase regulatory subunit-associated protein 3 (CDK5RAP3) in hepatocellular cancer and hepatocyte growth factor (HGF) and follicle-stimulating hormone (FSH) in ovarian cancer activate PAK4 to promote cell migration." (PMID 25975262, 2015). "Stable knockdown of Pak4 in ovarian cancer cell lines reduces cell migration, invasion and proliferation." (PMID 27919028, 2014). "To investigate the relevance of NAMPT and PAK4 in ovarian cancers, we first examined TCGA datasets." (PMID 38424218, 2024). "To better understand Pak4 regulation network that could affect ovarian cancer prognosis, we preformed GeneMANIA and String analysis." (PMID 38807162, 2024). "Two different microarrays were used to elucidate prognosis of Pak4 in ovarian cancer." (PMID 38807162, 2024). "Pak4 level was significantly correlated with different histological types of ovarian cancer." (PMID 38807162, 2024). "We investigated Pak4 expression in 163 ovarian cancer samples." (PMID 38807162, 2024). "In summary, our study proved that Pak4 was highly expressed in ovarian cancer." (PMID 38807162, 2024). "To explore the expression of Pak4 in ovarian cancer, we used GEPIA and Ualcan database." (PMID 38807162, 2024). "The data suggested that Pak4 might be used as a potential biomarker for predicting prognosis of ovarian cancer patients." (PMID 38807162, 2024). "Thus, it can be summarized that the proliferation of ovarian cancer cells is regulated by numerous factors, miR-24-1-5p and PAK4 are only the tip of the iceberg." (PMID 29440672, 2018). "Importantly, high PAK4 expression in ovary cancer was correlated with progressing disease stage, poor patient survival and to resistance to chemotherapy." (PMID 26554417, 2015). "The prognostic value and therapeutic potential of PAK4 has been confirmed in ovarian cancer." (PMID 26411419, 2015). "In ovarian cancer, Pak4 overexpression could promote cell migration, invasion and proliferation." (PMID 38807162, 2024). "Therefore, we investigated whether Pak4 expression showed any correlation with immune cells and immune biomarkers in ovarian cancer based on TCGA data." (PMID 38807162, 2024). "Therefore, it is urgent to know Pak4’s role in ovarian cancer tumorigenesis and prognosis." (PMID 38807162, 2024). "Therefore, Pak4 may affect tumorigenesis and prognosis of ovarian cancer patients through interacting with these proteins." (PMID 38807162, 2024). "Thus, Pak4 may play an important role in T cell exhaustion and immune escape of ovarian cancer microenvironment." (PMID 38807162, 2024). "Moreover, previous study revealed that PAK4 could induce the expression of cyclinD1 through PAK4/c-Src/EGFR pathway in ovarian cancer cells." (PMID 27077843, 2016). "Additionally, KPT-9274, a dual-specific inhibitor targeting PAK4 and nicotinamide phosphoribosyltransferase, effectively suppressed the growth, survival, and migration of triple-negative breast cancer 41, 42, kidney cancer 43, acute myeloid leukemia 44, and ovarian cancer cells." (PMID 39781524, 2025). "Therefore, Pak4 may be used as a promising prognostic biomarker for ovarian cancer." (PMID 38807162, 2024). "PAK4 overexpression has been shown to promote ovarian cancer cell migration and invasion in a c-Src and MEK-1 kinase-dependent manner, and induce cell proliferation through the Pak4/c-Src/EGFR (epidermal growth factor receptor) pathway." (PMID 27919028, 2014).
ovarian cancer (continued). "Pak4 has been proved to be tumorigenic in many types of cancers, but its role in ovarian cancer is still not clarified." (PMID 38807162, 2024). "Pak4 expression was negatively connected with OS and PFS of ovarian cancer patients." (PMID 38807162, 2024). "Pak4 was highly expressed in ovarian cancers, regardless of different FIGO stages and histological grades." (PMID 38807162, 2024). "We further identified Pak4 expression negatively correlated with OS and PFS of ovarian cancer." (PMID 38807162, 2024). "We figured out that Pak4 expression level was not correlated with tumor grade of ovarian cancer (P > 0.05)." (PMID 38807162, 2024). "Pak4 expression level was not correlated to stages or grades of ovarian cancer." (PMID 38807162, 2024). "Histological grades of ovarian cancer did not affect Pak4 expression level (P = 0.362)." (PMID 38807162, 2024).
melanoma (22 papers, 2014 to 2025). A malignant, usually aggressive tumor composed of atypical, neoplastic melanocytes. "High PAK4 expression is associated with limited infiltration of T cells and dendritic cells in immune checkpoint inhibitor-resistant melanoma patients." (PMID 38067120, 2023). "Higher levels of PAK4 expression were associated with reduced immune cell infiltration and contributed to making melanoma cells resistant to anti-PD-1 therapy through the β-catenin pathway." (PMID 36980457, 2023). "PAK4 expression partially rescued the effect of loss of endogenous PAK4 on cell migration in SBcl2 melanoma cells." (PMID 35969127, 2022). "Silencing of PAK4 impairs viability, migration and invasive behaviour of melanoma cells carrying BRAFV600E or NRASQ61K mutations." (PMID 35969127, 2022). "Of note, PAK4 overexpression is associated with tumorigenesis in several tumor types including breast, pancreatic, bladder, ovarian cancer, and melanoma, and constitutes a potential target for cancer treatment." (PMID 36588582, 2022). "In melanoma cell lines, depletion of PAK4 was associated with an increase in RhoA activity and a decrease in the percentage of cells with mature degradative invadopodia." (PMID 32309283, 2020). "We have shown that specific loss of PAK4 expression concomitantly reduces the invasive potential of melanoma cells and increases the level of RhoA activity." (PMID 27765920, 2016). "For example, both genetic knockdown and pharmacological inhibition of PAK4 showed drastic R-to-S shift ability in A375 (melanoma)." (PMID 38609378, 2024). "In melanoma, Cercam1, Enpep, Itga3, and Lgals3 expressions were higher in tumours with PAK4 inhibition, indicating changes in angiogenesis." (PMID 38067120, 2023). "Here, we identify PAK4 as an essential effector of an oncogenic signalling network in melanoma cells, consistent with emerging data pinpointing this specific group II PAK as an effector in Ras-driven tumours." (PMID 35969127, 2022). "Taken together, these results suggest that PAK4 has a predominant role in regulating cytoskeletal organisation and migration in melanoma cells." (PMID 35969127, 2022). "In multiple cancers including melanomas PAK5 most frequently carries non-synonymous mutations; PAK6 and PAK4 have fewer; and PAK4 is often amplified." (PMID 35969127, 2022). "SBcl2 melanoma cells carrying the NRASQ61K mutation are invasive, and the effects of knocking down PAK4 and PAK6 on their migration was analysed using a Transwell Matrigel migration assay." (PMID 35969127, 2022). "PAK4 is overexpressed in melanoma with poor T cell infiltration and facilitates the activation of the WNT/β-catenin pathway." (PMID 35800076, 2022). "Together these genomic, biochemical and cellular data suggest that the oncogenic properties of PAK4 are regulated by PKC–PKD signalling in melanoma, while PAK5 and PAK6 are dispensable in this cancer." (PMID 35969127, 2022). "To do so, we used transcriptomic data from multiple clinical datasets and compared melanoma tumors with high PAK4 expression versus low PAK4 expression." (PMID 36588582, 2022). "PAK4 mediates invadopodia maturation in melanoma cells by inhibiting postsynaptic density protein 95/disc-large/zonula occludens-RhoGEF (PDZ–RhoGEF)." (PMID 35800076, 2022). "A total of 44 murine melanoma B16 tumors (22 PAK4 KO and 22 WT) were then analyzed by flow cytometry using specific markers to characterize DCs." (PMID 36588582, 2022). "Although PAK4 expression is specifically knocked out in endothelial cells, there are some similarities with our melanoma PAK4 KO cells, stressing the importance of PAK4 in modulating the tumor microenvironment and impacting immunotherapy effectiveness." (PMID 36588582, 2022). "It should be mentioned that the antitumor activity of KPT-9274 in rhabdomyosarcoma, Ewing sarcoma, multiple myeloma, breast cancer, pancreatic ductal adenocarcinoma, colon carcinoma, and melanoma was shown to be substantially driven by PAK4 inhibition." (PMID 34068917, 2021).
melanoma (continued). "Because PAK4 plays a central role in melanogenesis, investigations into the mechanism by which deregulation of PAK4 contributes to the development of melanoma would be fruitful." (PMID 30755582, 2019). "Taken together our work points to essential requirements for both PAK1 and PAK4 during melanoma invasion and further provides clear evidence of differential function." (PMID 27765920, 2016). "We found PDZ-RhoGEF is expressed in both of our invasive melanoma cells and we have now confirmed the preferential binding of PAK4 to PDZ-RhoGEF." (PMID 27765920, 2016). "In this study we demonstrate that PAK1 and PAK4 expression at the protein level is significantly increased in melanoma compared to melanocyte controls using both cell lines and patient derived cell strains." (PMID 27765920, 2016). "PAK1 and PAK4 protein levels were elevated in invasive melanoma cell lines and cells derived from patient samples." (PMID 27765920, 2016). "This study used the invadopodia assay as an indicator of invasive potential, alongside a 3D and an in vivo invasion assay, to investigate the role of PAK1 and PAK4 in melanoma invasion." (PMID 27765920, 2016). "We found that depleting either PAK1 or PAK4 significantly reduced invadopodia maturation and subsequent matrix degradation in melanoma cells and found that PAK1 or PAK4 expression are required for efficient invasion in 3D and in vivo invasion assays." (PMID 27765920, 2016). "This study clearly demonstrates that PAK1 and PAK4 play an important role in melanoma cell invasion." (PMID 27765920, 2016). "However, genetic deletion of PAK4 reversed PD-1 blockade resistance by increasing CD8 T cell infiltration in mice carrying flank tumours of melanoma." (PMID 38067120, 2023). "More recently, it has been reported in melanoma that PAK4 expression was elevated in the patients’ samples with poor infiltrated immune cells and thus decreased the response to a PD-1 blockade, and that knockout of PAK4 enhanced the infiltration of CD8+ T cells, possibly by downregulation of PD-L1." (PMID 36672500, 2023). "Interestingly, in melanoma clinical datasets, PAK4 expression levels negatively correlate with the presence of CCL21, the ligand for CCR7 expressed in CD103+ DCs." (PMID 36588582, 2022). "In the genomes of specific cancers, namely breast, head-and-neck, liver, lung adenocarcinoma, squamous cell lung cancer, and melanomas, PAK5 frequently carries non-synonymous point mutations, and small insertions and deletions; PAK6 and PAK4 have fewer; and PAK4 is often amplified." (PMID 35969127, 2022). "We observed that blockade of PAK4 kinase activity was sufficient to overcome resistance to anti-PD-1 therapy in B16 melanoma cells as there was a significant reduction in tumor volume in B16 PAK4 KD cells treated with anti-PD-1 compared with those treated with isotype." (PMID 36588582, 2022). "Previously, we described an increase in T-cell infiltration in murine melanoma B16 PAK4 KO tumors." (PMID 36588582, 2022). "In contrast with PAK4, PAK5 was undetectable in the melanoma cells and its ectopic expression did not rescue the loss of PAK4." (PMID 35969127, 2022). "Furthermore, the importance of PAK4 deletion is also supported by the PAK4 inhibitor as well as the late in vivo RNA-seq data, where anti-PD-1 treatment only changed the transcriptome of melanoma PAK4 KO tumors." (PMID 36588582, 2022). "In melanoma, tumors with greater PAK4 expression were less responsive to anti-PD-1 therapy." (PMID 36594908, 2021). "To determine if common melanoma-associated PAK5 mutations affect enzymatic function, we immunoprecipitated individual PAK5 mutants from our hMELT stable cell lines and subjected these proteins to in vitro kinase assays using a canonical PAK4 peptide substrate." (PMID 29875996, 2018). "An increase in PAK4 mRNA in melanoma cell lines, compared to melanocytes, suggests that the upregulation may also be occurring at the transcriptional level." (PMID 27765920, 2016).
melanoma (continued). "PAK4 was robustly overexpressed in the melanoma cell lines, including the invasive cells." (PMID 27765920, 2016). "Therefore, using three different experimental assays we have demonstrated that reducing PAK1 or PAK4 expression can inhibit the invasion of melanoma cells." (PMID 27765920, 2016). "We now find that PAK4 depleted melanoma cells exhibit elevated levels of RhoA activity." (PMID 27765920, 2016). "Additionally, in this study, as PAK4 expression was linked to immune cell infiltration, IDO1 expression was similarly correlated with PD-L1 expression and the infiltration of FOXP3-positive cells in melanoma." (PMID 39273017, 2024). "In addition, PAK4 inhibition enhanced the effectiveness of PD-1 blockade therapy in melanoma cells." (PMID 36980457, 2023). "To validate loss of functionality at the PAK4 kinase domain, we evaluated whether B16 PAK4 KD cells had decreased phosphorylation of β-catenin S675 and reduced response to Wnt-3a stimulation, as we have previously observed in B16 PAK4 KO cells as well as in human melanoma PAK4 KO cells." (PMID 36588582, 2022). "Moreover, silencing of PAK4 impairs viability, migration, and invasive behaviour of melanoma cells." (PMID 35969127, 2022). "We have recently shown that in melanoma, PAK4 overexpression is associated with lack of immune cell infiltration and resistance to PD-1 blockade immunotherapy, with its inhibition resulting in increased immune cell infiltration leading to overcoming resistance to anti-PD-1 therapy." (PMID 36588582, 2022). "The genetic knockout of PAK4 augmented tumor infiltration by T cells and natural killer cells and pharmacological inhibition of PAK4 synergized with PD-1 blockade immunotherapy in melanoma mouse models, suggesting the possibility of enhancing the efficacy of immunotherapy also in KRAS mutant tumors." (PMID 33777798, 2021). "Our results suggest that both PAK1 and PAK4 could play a role during melanoma invasion." (PMID 27765920, 2016). "Interestingly, COSMIC reports a Ser99Phe mutation of PAK7 in a case of malignant melanoma, and ANIA predicts Ser99 as a candidate ‘lynchpin’ 14-3-3 binding phosphosite, which is conserved in human PAK4, 6 and 7, as well as the Branchiostoma and Ciona pro-orthologues." (PMID 24501395, 2014). "Inhibition of PAK4 enhanced the infiltration of CD103+ dendritic cells and CD8 T cells, and its expression correlates with CCL21 levels in melanoma biopsies." (PMID 38067120, 2023). "We therefore analysed the effect of silencing PAK4 and PAK6 expression on migration of melanoma cells." (PMID 35969127, 2022). "Ser99 and Ser181 of endogenous PAK4 are also phosphorylated in SKMEL13 (BRAFV600E) and SBcl2 (NRASQ61K) melanoma cells, indicating that relevant PKC(s) and PKD(s) are active in these cells." (PMID 35969127, 2022). "PAK4 and PAK6 are expressed to different levels in different melanoma cell lines, while PAK5 expression is low or undetectable in these cells." (PMID 35969127, 2022). "Inhibition of PAK4 increased the MHC I expression in oral squamous cell carcinoma but not in melanoma." (PMID 39941877, 2025). "We also describe how lack of PAK4 expression alters the tumor microenvironment and sensitizes murine melanoma to anti-PD-1 therapy from a transcriptomic perspective." (PMID 36588582, 2022). "To investigate this hypothesis, here we compare the cellular regulation of PAK4, PAK5 and PAK6, and investigate their relative roles in melanoma cells." (PMID 35969127, 2022). "Expression of PDZ-RhoGEF dominant negative mutants rescued invadopodia in PAK4-depleted melanoma cells, which suggests that a PAK4-mediated reduction in RhoA activity is required for invadopodium maturation." (PMID 32309283, 2020). "Therefore, lack of PAK4 expression facilitates changes in the tumor microenvironment, which become more evident when given anti-PD-1 therapy, to sensitize melanoma B16 tumors to anti-PD-1 treatment." (PMID 36588582, 2022).
melanoma (continued). "This also suggests that the effect of PAK4 inhibition on cancer cell surface MHC I expression is likely cancer-specific, given that it has been observed in PDA and oral SCC but not in melanoma." (PMID 39941877, 2025). "Together these findings indicate that only PAK4, but not PAK5 and PAK6, can complement the requirement for survival and migration of melanoma cells." (PMID 35969127, 2022).
hepatocellular carcinoma (18 papers, 2015 to 2025). A malignant tumor that arises from hepatocytes. "Recently, PAK4 inhibition was found to induce autophagy in a human hepatocellular carcinoma (HCC) cell line causing G2/M cell cycle arrest and reducing cancer cell proliferation." (PMID 39941877, 2025). "In hepatocellular carcinoma, its inhibition of the PAK4/Raf/MEK/ERK pathway contributes to its tumor-suppressive role." (PMID 41154751, 2025). "Furthermore, PAK4 knockdown (KD) in the human hepatocellular carcinoma (HCC) HepG2 cell line induced autophagy and caused G2/M cell-cycle arrest." (PMID 39941877, 2025). "PAK4 has been shown to be controlled by miRNA-433 and subsequently attenuates Akt signaling, resulting in regulating the proliferation of hepatocellular carcinoma (HCC) cells." (PMID 28706947, 2017). "Similarly, miR-199a-3p-expressing AT-MSC-derived EVs induce sensitivity to doxorubicin via the downregulation of mTOR and p21-activated kinase 4 (PAK4) in hepatocellular carcinoma cells." (PMID 37175226, 2023). "A previous study demonstrated that PAK4 could be a direct target of MiR-199a-3p in hepatocellular carcinoma." (PMID 36523634, 2022). "However, data from hepatocellular cancer indicates CDK5RAP3 promotes metastasis through the activation of PAK4." (PMID 31061682, 2019). "However, miR-199a-3p is frequently downregulated in hepatocellular carcinoma, where it targets PAK4, CD44, and mTOR [14, 15, and 16] and displays antiproliferative/tumor suppressor functions." (PMID 25839163, 2015). "MiR-199a/b-3p could suppress hepatocellular carcinoma through inhibiting PAK4/Raf/MEK/ERK pathway." (PMID 35842733, 2022). "We observe impaired ketogenesis and increases in PAK4 protein and NCoR1 phosphorylation levels in liver tissues of high fat diet-fed mice, NAFLD patients, and hepatocellular carcinoma patients." (PMID 37591884, 2023). "In hepatocellular cancer, CDK5RAP3 was reported to promote metastasis through PAK4 activation." (PMID 31061682, 2019). "The sucessful tumor cell integration of these multi-functionalized nanoparticles proved to drastically suppress tumorigenesis by targeting mTOR, PAK4, RHOC, and the epithelial–mesenchymal transition (EMT) in hepatocellular carcinoma (HCC) PDX models." (PMID 35954481, 2022).